IL6 (interleukin 6)
Diseases named in the same sentence as IL6 in open-access papers (continued):
Sharing a sentence is not in itself a finding about the gene and the disease.
nasal polyps (continued). "The 487-fold induction seen for TSLP in nasal polyposis is much stronger that the induction seen for IL-6 and IL-8 in healthy epithelium and furthermore the induction of IL-6 or IL-8 is not affected by the diseased state." (PMID 27050744, 2016). "Other researchers have also found that the use of an MIF inhibitor decreased IL-6-mediated inflammation in nasal polyps." (PMID 25705692, 2015). "Increased IL-6 and IL-8 production following exposure to LPS were decreased by LPS-RS in nasal polyp organ cultures." (PMID 25390332, 2014). "Both oncostatin M (OSM) and IL-6 are locally produced in nasal polyps and may contribute to pathology by negatively impacting epithelial barrier function." (PMID 40453660, 2025). "A previous report indicated that IL-6 could be a major cytokine in nasal polyp physiopathology, possibly playing an important role in promoting significant increases in plasma cells and antibodies." (PMID 38773574, 2024). "Our hypothesis was that among the inflammatory cytokines involved in nasal polyps, some of the IL-6 cytokine family could alter epithelial repair mechanisms." (PMID 37047067, 2023). "For example, IL-6 may act as a proinflammatory and proangiogenic mediator in nasal polyps, contributing to chronic inflammation and polyp growth." (PMID 37176721, 2023). "IL-6 has been shown to influence wound repair in in vitro studies and may further lead to cell proliferation observed in nasal polyps." (PMID 36285981, 2022). "This suggests IL-6’s strong involvement in nasal polyp pathogenesis." (PMID 36285981, 2022). "IL-6 strongly correlates with other cytokines as well as with the proliferation marker Ki-67 which suggests significant stimulation of this regulatory cytokine and its possible involvement in the pathogenesis of recurrent nasal polyps." (PMID 36285981, 2022). "Therefore, our aim is to investigate the complex appearance, relative distribution and interlinks of IL-1, IL-4, IL-6, IL-7, IL-8, IL-10, IL-12 and Ki 67 in chronic rhinosinusitis with nasal polyps (CRSwNP) affected human nasal mucosa." (PMID 34208325, 2021). "Expression of TRPC5 in nasal polyps was positively correlated with the number of eosinophils, IL-6 expression and inflammation, suggesting that these pathways may respond differently to different inflammatory responses." (PMID 34836549, 2021). "Here, primary HNEC cultures revealed a relationship between IL-6 and epithelial cells, suggesting that IL-6 could be involved in the growth of nasal polyps." (PMID 32209102, 2020). "Consequently, in this study we chose to unravel the specific role of IL-6 in nasal polyposis as a potential target for new monoclonal therapies in CRSwNP." (PMID 32209102, 2020). "Additionally, frontal recess mucosa showed significantly higher levels of IL-6 compared with ethmoid sinus mucosa and nasal polyp." (PMID 28464955, 2017). "Decrease of IL-6 in both—epithelium and connective tissue with strong correlation between it and IL-7 and IL-10 in connective tissue suggests significant stimulation of this regulatory cytokine and, possibly, the important role in pathogenesis of the development in nasal polyps." (PMID 34208325, 2021). "Our aim was to use detected IL-1, IL-4, IL-6, IL-7, IL-8, IL-10, IL-12, Ki 67, HBD-2, HBD-3, and LL-37 to classify specific inflammatory endotypes in chronic rhinosinusitis with the tissue of nasal polyps (CRSwNP)." (PMID 38791197, 2024). "First, we analyzed IL-6 and OSM expression, the secretion of OSM in outer space, and epithelial TJ expression patterns in nasal polyps." (PMID 37047067, 2023). "Besides IL-6, epithelial IL-1α had strong correlations with various factors without a distinctive pattern, and it could be presumed that it functions as an alarmin and has no specific role in inflammation that advances the formation of nasal polyps." (PMID 36285981, 2022).
nasal polyps (continued). "Andrographolide significantly inhibits interleukin-6 and interleukin-17 production in monocytes isolated from CRS patients with nasal polyp." (PMID 33912859, 2021). "In this study, a significant increase in IL-6 expression was noted in the frontal recess mucosa in the ECRS group as compared with the ethmoid sinus mucosa and nasal polyp in the ECRS group." (PMID 28464955, 2017). "To confirm the inhibitory effect of TLR4 antagonist on production of IL-6, IL-8, and MMP-1 in human tissues, we cultured nasal polyp organ cultures and treated the cells with LPS in the presence or absence of LPS-RS." (PMID 25390332, 2014). "In this study, we explored the role of TLR4 in gene expression of immune responses leading to IL-6, IL-8, and MMP-1 production after LPS stimulation in nasal polyp." (PMID 25390332, 2014). "Therefore, our aim was to use detected IL-1, IL-4, IL-6, IL-7, IL-8, IL-10, IL-12, Ki 67, HBD-2, HBD-3, and LL-37 to classify specific inflammatory endotypes in chronic rhinosinusitis with the tissue of nasal polyps (CRSwNP)." (PMID 38791197, 2024). "Our hypothesis was that among the inflammatory cytokines involved in nasal polyps, OSM and IL-6 could alter epithelial repair mechanisms." (PMID 37047067, 2023). "IL-5, IL-6, and IL-10 levels were significantly increased in asthmatic patients with nasal polyps compared with non-asthmatic patients with nasal polyps." (PMID 29564208, 2018). "In contrast, IL-6 expression in the frontal recess mucosa was not significantly different compared with the ethmoid sinus mucosa and nasal polyp in non-ECRS group." (PMID 28464955, 2017). "We showed that IL-6, IL-8 and MMP-1were produced by LPS in nasal polyp-derived fibroblasts." (PMID 25390332, 2014). "Additionally, we found that expression of IL-6, IL-8, and MMP-1 is stimulated by LPS via TLR4 in nasal polyp organ cultures." (PMID 25390332, 2014). "Commonly, IL-6 could contribute to exaggerated epithelial reaction and growth of nasal polyps, which, probably, is not the most characteristic feature in our patients." (PMID 34208325, 2021). "However, the TLR7/8 agonist R848 triggers the induction of IL-33 in healthy epithelium only (23.2 ± 6.17, p < 0.05) and not nasal polyposis epithelium (1.57 ± 0.38), despite the IL-6 and IL-8 induction levels being similar between those two groups." (PMID 27050744, 2016). "Indeed, the effect of IL-4/IL-13 and IL-5 on nasal epithelial repair was already showed but to date, no study has precisely described the role of IL-6, IL-9 and IL-10 (new ILs described in nasal polyposis) on human nasal epithelial cells in an in vitro wound repair model." (PMID 32209102, 2020). "In nasal polyps and in non-inflammatory nasal mucosa, we compared the expression of OSM and IL-6 in RT-qPCR." (PMID 37047067, 2023). "Just like previously reported for primary healthy nasal epithelium, also here in epithelium of nasal polyps, despite the presence of TLR4 LPS did not induce IL-6 or IL-8." (PMID 27050744, 2016). "This inductor, such as fungi, bacteria, or lipopolysaccharides (the main outer surface membrane component of Gram-negative bacteria), could increase IL-6 and OSM expression in nasal polyps." (PMID 37047067, 2023).
peripheral arterial disease (28 papers, 2008 to 2025). A disorder of the arteries supplying the upper and lower extremity and the visceral organs. "In studies designed to identify plasma predictors of peripheral arterial disease (PAD), the downstream induced protein of IL-6, CRP, is strongly and independently associated with symptomatic PAD." (PMID 19936194, 2008). "IL-6 is produced by hypoperfused skeletal muscle in the patients with peripheral artery disease and, in addition, it is systematically released in the reperfusion phase of aortic aneurysm surgery." (PMID 24575415, 2014). "The aim of this study was to investigate the potential role of HMGB-1, OPG and several inflammatory mediators such as C-reactive protein (HsCRP), tumor necrosis factor-alpha and interleukin-6 (IL-6) on the presence and severity of peripheral artery disease in patients with T2D." (PMID 28789654, 2017). "The results revealed that serum IL-6 level in type II diabetes mellitus (T2DM) with peripheral arterial disease (PAD) patients was increased significantly (85.93) as compared to T2DM patients (59.52) and healthy individuals (4.81)." (PMID 38961103, 2024). "Interestingly, IL6 upregulation was identified in peripheral artery disease." (PMID 34169069, 2021). "In skeletal muscle, the expression of TNF-alpha, INF-gamma, IL-17A, IL-6, CCL5, and TGF-beta were increased in patients with peripheral arterial disease (PAD)." (PMID 36579591, 2022). "In support of this theory, it was shown that the circulating levels of cytokines (IL-6 and TNFα), adhesion molecules (VCAM-1 and ICAM-1), and selectins in patients with peripheral arterial disease are elevated." (PMID 34447794, 2021).
autism spectrum disorder (27 papers, 2015 to 2026). A spectrum of developmental disorders that includes autism, and Asperger syndrome. "High levels of IL-6 are associated with more severe autism spectrum disorder, a greater presence of stereotyped behavior, greater hyperactivity, and higher levels of intellectual disability." (PMID 39189164, 2024). "Autism spectrum disorders (ASDs) have been associated with brain inflammation as indicated by microglia activation, as well as brain expression and increased plasma levels of interleukin-6 (IL-6) and tumor necrosis factor (TNF)." (PMID 26418275, 2015). "Most recently, IL-17a, a downstream product of IL-6, from a subset of T helper cells was found to cause cortical defects and is associated with autism-spectrum disorder behavior in offsprings, providing relevance to the finding that the mother’s immune system during pregnancy impacts fetal outcome." (PMID 40710297, 2025). "It has been suggested that the underlying mechanism of autism spectrum disorders might be brain inflammation associated with increased inflammatory cytokines such as IL-6 and TNF-α." (PMID 38905296, 2024). "Prenatal maternal immune activation (MIA) has been implicated in autism spectrum disorder (ASD) pathogenesis, with interleukin-6 (IL-6) identified as a key inflammatory mediator." (PMID 41150800, 2025). "The findings of this study pointed to the existence of a correlation between the levels of expression of the genes JAK1 and IL-6 and the severity of autism spectrum disorder (ASD)." (PMID 38026692, 2023). "Numerous studies have provided evidence highlighting the significance of pro-inflammatory cytokines, namely IL1, IL-6, IL-18, and TNFα, in the development of atypical behavior in children diagnosed with autism spectrum disorder." (PMID 38026692, 2023). "As an example, IL-1β and IL-6 has been found increased in maternal serum, amniotic fluid, and serum of children subsequently diagnosed with autism spectrum disorders (ASD) as well as in the well-known maternal immune activation rodent model." (PMID 38052845, 2023). "Some patients with autism spectrum disorders (ASDs) have an augmented level of proinflammatory cytokines IL-12, IL-6 and IL-1β, while IFNγ and the anti-inflammatory cytokine IL-10 seem to be reduced." (PMID 36835652, 2023). "Samples from the brain and cerebrospinal fluid of patients with autism spectrum disorders show increased contents of inflammatory molecules, such as IL-1β, IL-6, TNF-α, MCP-1, and CXCL8/IL-8." (PMID 33506033, 2021). "In another meta-analysis patients with an autism spectrum disorder were reported to have increased blood concentrations of IL-1β, IL-6, IFN-ɣ and TNF-α." (PMID 34589729, 2021). "The inhibition of GSK-3β via targeting the IL-6-mediated PI3/AKT/mTOR pathway decreases neural apoptosis and affects autism spectrum disorder via GRPR." (PMID 40843259, 2025). "Keywords including "autism spectrum disorder," "oxytocin," "GABA," "Serotonin," "CRP," "IL-6," "Fe," "Zn," "Cu," and "gut microbiota" were used for the search." (PMID 38283894, 2024). "Also, it has been demonstrated that vinpocetine suppressed elevated brain levels of IL-6 and TNF-α, and augmented brain level of IL-10, in a rat model of autism spectrum disorder." (PMID 36594060, 2023). "IL-6 activates other signaling pathways, such as the PI3K/AKT/the mammalian target of rapamycin (mTOR) glycogen synthase kinase-3 beta (GSK-3β) and gastrin-releasing peptide (GRP) receptor (GRPR) pathways, in hippocampal neurons of mice with autism spectrum disorder." (PMID 40843259, 2025).
bone cancer (27 papers, 2010 to 2025). A primary or metastatic malignant neoplasm affecting the bone or articular cartilage. "Therefore, here we review the current evidence of the role of IL-6 in the generation of pathological pain caused by bone cancer, peripheral nerve injury, spinal cord injury, chemotherapy-induced peripheral neuropathy, complete Freund’s adjuvant (CFA) injection, or carrageenan injection." (PMID 27267059, 2016). "IL-6 is thought to contribute to the generation of bone cancer pain, through overexcitability of dorsal root ganglion neurons and upregulation of transient receptor potential channel vanilloid subfamily member 1 in dorsal root ganglion neurons." (PMID 35262711, 2022). "In bone cancer pain model rats, IL-6 can up-regulate the expression of the TRPV1 protein in the dorsal root ganglia through the Janus kinase (JAK)/phosphatidylinositol 3-kinase (PI3K) pathway and participate in peripheral sensitization." (PMID 35800014, 2022). "It was demonstrated that intrathecal injection of agents activating CB2 inhibits glial cells and downregulates the expression of IL-1β and IL-6, reducing bone cancer pain." (PMID 34576321, 2021). "Blockade of IL‐6 in a rat model of bone cancer reduced mechanical hypersensitivity and ongoing pain, and prevented bone degradation, without affecting tumour burden." (PMID 32955748, 2021). "IL-6 and interleukin-17 (IL-17) induced neuropathic manifestations in animal models of bone cancer." (PMID 39940997, 2025). "For instance, the up-regulation of tumour necrosis factor-α (TNF-α) and interleukin-6 (IL-6) in bone metastases may activate TRPA1 in the sensory neurons of bone cancer rats and contribute to CIBP." (PMID 39940997, 2025). "This study found that intrathecal injection of hPPE-modified hBM-MSCs could effectively relieve bone cancer pain in rats by inhibiting the expression of pro-inflammatory cytokines, including IL-1β and IL-6." (PMID 39020426, 2024). "Then, microglial activation with an increase in inflammatory cytokines in bone cancer pain rats was imitated using an LPS treatment in vitro; and miR-155-5p knockdown alleviated the augment of Tnf, Il1b, and Il6, which was possibly achieved by suppressing Sgk3 in vitro." (PMID 36143385, 2022). "The results showed that intrathecal injection of miR-9-5p modified BM-MSCs could reduce the expression of REST and increase the expression of MOR, inhibit the release of inflammatory factors TNF-α, IL-6, and IL-1β in the spinal cord dorsal horn of mice, and relieve bone cancer pain." (PMID 39020426, 2024). "Several pro-inflammatory cytokines (IL-1β, TNFα, IL-6, and TGFβ) and inflammatory mediators (CGRP) are increased in the DRG in response to bone cancer and fracture." (PMID 27199772, 2016). "Increased expression of spinal SP, CGRP, and other inflammatory mediators (TNF, IL-1, IL-6, CCL2, and nerve growth factor) are observed in the spinal cord of rats with fracture-induced and bone cancer-induced pain." (PMID 27199772, 2016). "Both inflammatory cytokines TNF (α) and IL6 regulate bone cancer pain via TRPA1, but no data have proven the relationship between TRPA1 and tumours." (PMID 39770499, 2024). "Increased IL-6 expression was decreased after MZL injection, indicating that TSPO may play a protective role in bone cancer-induced inflammation." (PMID 36071748, 2022). "In bone cancer pain, short-term exposure of cancer-related fibroblasts, MSCs, and osteoblasts to pH 6.8 can promote the expression of inflammatory and nociceptive mediators (NGF, BDNF, IL-6, IL-8, IL-1b, and CCL5), leading to nociceptor sensitization and hyperalgesia." (PMID 39679363, 2024). "A subpopulation of osteoblasts was identified in the bone tumor microenvironment in vivo of both humans and mice with bone metastatic breast cancer that express RUNX2/OCN/OPN but is negative for IL-6 and alpha-smooth muscle actin." (PMID 30813947, 2019).